TMEM140 (transmembrane protein 140)
Synonyms: FLJ11000
Tractability: Antibody: UniProt predicts a signal peptide or a membrane-spanning region. PROTAC: ubiquitination databases record sites on it.
Gene: Protein-coding gene on chromosome 7 (135,148,072 to 135,166,519, forward strand). Ensembl gene ENSG00000146859.
Subcellular location: Membrane
Gene Ontology:
Molecular function: protein binding
Cellular component: membrane
Genetic constraint (gnomAD): Loss-of-function variants: 1 observed, 0.59 expected, observed/expected ratio (o/e) 1.69, 90% interval 0.33 to 1.92. That is too few expected variants to judge how well the gene tolerates losing a copy. Missense variants: 227 observed, 228.67 expected, observed/expected ratio (o/e) 0.99, 90% interval 0.89 to 1.11. Synonymous variants: 102 observed, 107.52 expected, observed/expected ratio (o/e) 0.95, 90% interval 0.81 to 1.12.
Homologues: Orthologues: chimpanzee TMEM140 (97% identical), macaque TMEM140 (82% identical), dog TMEM140 (73% identical), rabbit TMEM140 (71% identical), pig TMEM140 (70% identical), guinea pig TMEM140 (69% identical), rat Tmem140 (66% identical), mouse Tmem140 (62% identical).
Diseases named in the same sentence as TMEM140 in open-access papers:
TMEM140 is named in the same sentence as 10 diseases in open-access papers, as found by Europe PMC text mining. Sharing a sentence is not in itself a finding about the gene and the disease. The quoted sentences say what the papers report.
glioma (5 papers, 2015 to 2024). A benign or malignant brain and spinal cord tumor that arises from glial cells (astrocytes, oligodendrocytes, ependymal cells). "Among these oncogenes, overexpression of NUAK2 promotes proliferation and invasion of A172,GLI1 is a well-known glioma-associated transcription factor; suppression of TMEM140 attenuates growth of glioma cell." (PMID 35521558, 2022). "To address the mechanism underlying the growth suppression of glioma cells by TMEM140 knockdown, we then determined the cell cycle profile of the TMEM140-silenced cells through flow cytometry." (PMID 26198430, 2015). "TMEM140 over-expression was strongly correlated with tumor size, histologic grade, and overall survival time in patients with gliomas." (PMID 29510530, 2018). "In glioma, TMEM140 expression has been analyzed in 47 of the 70 glioma samples by immunohistochemistry." (PMID 30574087, 2018). "Note that the control brain tissues had lower expression levels of TMEM140 protein compared with the glioma tissues." (PMID 26198430, 2015). "In the present study, we found that TMEM140 was frequently overexpressed in 67.1 % (47/70) of the glioma tissues." (PMID 26198430, 2015). "To address the efficacy of TMEM140 on glioma cells, we knocked down TMEM140 in the glioma cell lines." (PMID 26198430, 2015). "Immunohistochemical analysis and real-time reverse transcription PCR were performed to detect the expression levels of TMEM140 in 70 glioma brain tissue samples." (PMID 26198430, 2015). "This study highlights the importance of TMEM140 as a novel prognostic marker and as an attractive therapeutic target for gliomas." (PMID 26198430, 2015). "The aim of the current study was to determine the clinical significance of TMEM140 expression in patients with gliomas and its effect on tumor cell malignant phenotypes." (PMID 26198430, 2015). "Next, we reanalyzed the high throughput RNA-sequencing data from the GBM cohort of the Cancer Genome Atlas (TCGA), and we found that TMEM140 expression was significantly increased in glioma tissue compared with normal brain tissue (P < 0.001)." (PMID 26198430, 2015). "We evaluated the expression levels of TMEM140 in five glioma cell lines (i.e., U87, U251, SHG44, U373, and T98G) through RT-PCR and Western blot analysis." (PMID 26198430, 2015). "It was observed that patients with gliomas expressing high levels of TMEM140 showed statistically poorer prognoses compared with patients with gliomas expressing low levels of TMEM140- (P = 0.019)." (PMID 26198430, 2015). "Our data demonstrated that TMEM140 is not only a prognostic biomarker but also a therapeutic target in human gliomas." (PMID 26198430, 2015). "Cell growth analysis was performed for two glioma cell lines (U87 and U373) transfected with TMEM140-RNAi-2, which were then subjected to cell growth analysis." (PMID 26198430, 2015). "TMEM140 knockdown in the glioma cells induced cell apoptosis at approximately 12-fold the rate in the corresponding normal control cells." (PMID 26198430, 2015). "We quantified the expression level of TMEM140 in glioma tissues compared with the control brain tissues (60 gliomas and 14 controls) using real-time reverse transcription PCR (RT-PCR) analysis." (PMID 26198430, 2015). "TMEM140 expression was inhibited in two glioma cell lines (i.e., U87 and U373) using a knockdown method with small interfering RNA." (PMID 26198430, 2015). "TMEM140 protein expression was significantly higher in gliomas than in normal brain tissues (p < 0.0001)." (PMID 26198430, 2015). "Next, the correlation between the TMEM140 expression levels and the clinical characteristics and outcomes of glioma patients was statistically analyzed." (PMID 26198430, 2015). "Our data suggest that TMEM140 can be a novel prognostic factor and potential treatment target for gliomas." (PMID 26198430, 2015).
glioma (continued). "The present study demonstrated the overexpression of TMEM140 in glioma tissues and analyzed the prognostic significance of TMEM140 expression in a large number of patients with gliomas." (PMID 26198430, 2015). "In a cell viability assay, both glioma cell lines showed significant reductions in cell viability through TMEM140 silencing compared with normal control cells." (PMID 26198430, 2015). "Therefore, TMEM140 has been proposed as a novel prognostic marker and as a potential therapeutic target for gliomas." (PMID 29510530, 2018). "Indeed, when TMEM140 is silenced in two glioma cell lines in vitro, U87 and U373, the proliferation decreased with a higher proportion of cells in G1 phase and the cell viability decreased due to the activation of the apoptotic pathway." (PMID 30574087, 2018). "TMEM140 has been involved in the regulation of the growth of glioma in vitro and in vivo." (PMID 30574087, 2018). "TMEM140 can be observed in 67.1 % (47/70) of the glioma specimens." (PMID 26198430, 2015). "In conclusion, we found for the first time that TMEM140 accumulates in gliomas." (PMID 26198430, 2015). "The effect of TMEM140 on apoptosis in glioma cells was investigated." (PMID 26198430, 2015). "TMEM140 gene is located on chromosome 7, and alterations of chromosome 7 are closely related to various cancers, such as breast cancer, prostate cancer, and gliomas." (PMID 26198430, 2015). "Our results suggest that TMEM140 expression is a prognostic factor that might play an important role in the viability, migration, and invasion of glioma cells." (PMID 26198430, 2015). "To test this hypothesis, we examined the expression status of TMEM140 and the clinicopathologic features, as well as the biological significance of its expression in glioma cell lines." (PMID 26198430, 2015). "We hypothesized that the overexpression of TMEM140 may promote tumor cell growth in gliomas." (PMID 26198430, 2015). "TMEM140 silencing could suppress the viability, migration, and invasion of glioma cells." (PMID 26198430, 2015). "Moreover, down-regulation of TMEM140 expression suppressed cell proliferation, migration, and invasion in two glioma cell lines (U87 and U373), which indicated that TMEM140 could be a potential therapeutic target of gliomas and warrants further investigation." (PMID 26198430, 2015). "Genes like TMEM140 and GPX8 also play regulatory roles in gliomas." (PMID 38809929, 2024). "Furthermore, TMEM140 knockdown remarkably decreased the protein levels of ICAM1, VCAM1, and Syndecan1, which are considered to be important in glioma cell migration and invasion." (PMID 26198430, 2015). "However, the function of TMEM140 in gliomas has not been thoroughly elucidated." (PMID 26198430, 2015).
gastric cancer (2 papers, 2015 to 2023). A primary or metastatic malignant neoplasm involving the stomach. "miR-135a-5p targets CASP1, CXCL10, and transmembrane protein 140 (TMEM140), which are known to be involved in the proliferation of gastric cancer cells and the expression of IFN-α." (PMID 37952025, 2023). "TMEM140 is identified as an amplified gene in the human gastric cancer genome." (PMID 26198430, 2015). "Although TMEM140 has been identified as an amplified gene in the human gastric cancer genome, to the best of our knowledge, there have been no reports describing the functions of TMEM140 in tumorigenesis and development of tumors." (PMID 26198430, 2015).
cancer (4 papers, 2015 to 2021). A tumor composed of atypical neoplastic, often pleomorphic cells that invade other tissues. "Genes whose upregulation is associated with some cancers (TMEM140, ANXA10, ZNF69, CA9, LOXL2, PAGE3, ELFN1) were also on this list, as was a putative tumor suppressor (DEC1)." (PMID 33601339, 2021). "Even though the biological functions of TMEM140 and TEAD2 seem relevant in cancer development and progression, in D842V mutant GIST these proteins were found mutated in only one patient and therefore no definitive conclusion can be realistically drawn." (PMID 29510530, 2018).
tumor (4 papers, 2015 to 2021). "Based on GSEA of the TCGA GBM dataset, we found that TMEM140 was associated with cellular adhesion molecules, which have been implicated in tumor progression." (PMID 26198430, 2015). "Consequently, the results implied that large tumor size, high histologic grade, and low patient survival rates were associated with high TMEM140 expression levels." (PMID 26198430, 2015). "TMEM140 overexpression was strongly correlated with tumor size, histologic grade, and overall survival time (P < 0.05)." (PMID 26198430, 2015). "At the end point, the tumor volumes were 498.4 ± 62.0 and 1145.1 ± 145.4 mm3 in the TMEM140-RNAi and normal control groups, respectively (P < 0.01)." (PMID 26198430, 2015). "We also found that the in vivo tumor growth and weight in the TMEM140-RNAi group were strongly inhibited compared with the normal control group." (PMID 26198430, 2015). "The higher level of TMEM140 is strongly correlated with tumor size, histologic grade, and overall survival time in this disease." (PMID 26198430, 2015). "A chi-square test showed that the increased expression level of TMEM140 was significantly correlated with tumor size (P = 0.0211) and pathological grade (P = 0.0108)." (PMID 26198430, 2015). "The level of TMEM140 in the tumor tissues was significantly higher than that in the controlled brain tissues (2.21 ± 0.11 vs. 0.87 ± 0.07, respectively, P < 0.0001)." (PMID 26198430, 2015). "The expression of TMEM17, TMEM97, TMEM140, TMEM156, TMEM173, and TMEM206 show significant correlation with immune, stromal, and ESTIMATE scores which indicates a strong association between those TMEMs and immune response inside a tumor microenvironment." (PMID 34638224, 2021). "Together with TMEM140, TEAD2, OR1J2, and GRIN2B, many other genes were commonly mutated across the tumor samples, however the recurrence always occurred when examining multiple metastatic samples of the same individual (T07–11 or T04–05 corresponding respectively to patients P06 and P04)." (PMID 29510530, 2018). "Notably, additional molecular events such as mutations in TMEM140 and TEAD2 were found to be shared in all the five geographically distinct tumor specimens obtained from the same individual." (PMID 29510530, 2018). "TMEM140 decreased cell viability in vitro and dramatically decreased tumor volume in vivo." (PMID 26198430, 2015). "Furthermore, the tumor weights were 0.44 ± 0.04 and 0.24 ± 0.04 g in the TMEM140-RNAi and normal control groups, respectively (P < 0.01)." (PMID 26198430, 2015).
TMEM140 also shares sentences with these, for which no sentence is quoted: breast carcinoma (1 paper); glioblastoma (1); periodontal disease (1); periodontitis (1); prostate carcinoma (1); systemic lupus erythematosus (1).